ZNF417 (zinc finger protein 417)
Description:
May be involved in transcriptional regulation.
Synonyms: MGC34079
Tractability: PROTAC: ubiquitination databases record sites on it.
Gene: Protein-coding gene on chromosome 19 (57,900,296 to 57,916,610, reverse strand). Ensembl gene ENSG00000173480.
Subcellular location: Nucleus
Subcellular location (Human Protein Atlas): Nucleoplasm; Nucleoli
Pathways (Reactome):
Gene expression (Transcription): Generic Transcription Pathway
Gene Ontology:
Molecular function: protein binding; DNA-binding transcription factor activity, RNA polymerase II-specific; RNA polymerase II cis-regulatory region sequence-specific DNA binding; sequence-specific double-stranded DNA binding
Biological process: regulation of transcription by RNA polymerase II; regulation of DNA-templated transcription
Cellular component: nucleus
Genetic constraint (gnomAD): Loss-of-function variants: 6 observed, 7.97 expected, observed/expected ratio (o/e) 0.75, 90% interval 0.41 to 1.47. That is too few expected variants to judge how well the gene tolerates losing a copy. Missense variants: 437 observed, 644.54 expected, observed/expected ratio (o/e) 0.68, 90% interval 0.63 to 0.73. Synonymous variants: 147 observed, 216.09 expected, observed/expected ratio (o/e) 0.68, 90% interval 0.59 to 0.78.
Homologues: Paralogues in human: ZNF587 (98% identical), ZNF776 (52% identical), ZNF17 (43% identical), ZNF416 (42% identical), ZNF530 (42% identical), ZNF287 (35% identical), ZNF34 (34% identical), ZKSCAN7 (32% identical), ZNF527 (32% identical), ZNF285 (32% identical), ZNF852 (31% identical), ZNF214 (31% identical), and 38 more.
Diseases named in the same sentence as ZNF417 in open-access papers:
ZNF417 is named in the same sentence as 6 diseases in open-access papers, as found by Europe PMC text mining. Sharing a sentence is not in itself a finding about the gene and the disease. The quoted sentences say what the papers report.
lymphoma (1 paper, 2025). A malignant (clonal) proliferation of B- lymphocytes or T- lymphocytes which involves the lymph nodes, bone marrow and/or extranodal sites. "Along these lines, we have recently shown that depleting ZNF417 and ZNF587, two primate-specific KZFPs frequently upregulated in lymphoma cells, induces H3K9me3 loss and replication stress at their target sites." (PMID 40555235, 2025).
viral infection (1 paper, 2023). "We also performed viral infection experiments in 293T cells transfected with GFP-fused KZFPs, including the PBS-Pro-binding human ZNF506 and mouse ZFP809 proteins, and the PBS-Lys-binding human ZNF417 and mouse ZFP961 proteins." (PMID 37697430, 2023).
cancer (1 paper, 2019). A tumor composed of atypical neoplastic, often pleomorphic cells that invade other tissues. "Two other genes, ZNF417 and KDM6B, have been associated as part of a gene signature with cancer aggressiveness." (PMID 31323891, 2019).
infection (1 paper, 2023). The state of being infected such as from the introduction of a foreign agent such as serum, vaccine, antigenic substance or organism. "FACS analysis determining the ratios of RFP+ cells in GFP+ cells revealed that ZNF506 overexpression significantly reduced pMX-RFP pseudoviral infectivity, compared with WT cells or control cells overexpressing ZNF417, but showed much less repression of pBABE-RFP pseudoviral infection." (PMID 37697430, 2023).
ZNF417 also shares sentences with these, for which no sentence is quoted: Hypertension (1 paper); tumor (1).